TNF (tumor necrosis factor)
Diseases named in the same sentence as TNF in open-access papers (continued):
Sharing a sentence is not in itself a finding about the gene and the disease.
infection (continued). "We also observed remarkable increases in IL-1β, IL-2, IL-10 and TNF-α at 7 dpi after which IL-1β and IL-2 dropped to pre-infection levels, IL-10 and TNF-α decreased to lower levels than pre-infection levels." (PMID 24465897, 2014). "Infection of macrophages and microglia can lead to cell activation and production of neurotoxic cytokines including TNF-α and the viral proteins includinHIV-1 Tat, which can directly or indirectly lead to neuronal damage and apoptosis." (PMID 24505242, 2014). "The results confirmed up-regulation of TGF-β and down regulation of TNF-α in tissue and serum level in PbA infected peptide treated mice compared to PbA infection." (PMID 24618707, 2014). "qRT-PCR test showed that after 4 hours of ST169 (H1N1) infection, compared with the 4 hours control, AM expressed dramatically higher levels of M1 markers, including TNF-α, MCP-1, iNOS, IL6 and IL-12." (PMID 25105760, 2014). "At early stages of infection the permeability of lung vasculature is increased due to enhanced release of proinflammatory cytokines (TNF-α, IFN-γ and IL-6)." (PMID 24565171, 2014). "Challenge with the respiratory pathogen induced an early increase (12 hours post-infection) of TNF-α, IL-1β and IL-6 levels and a late increase of IFN-γ (48 hours post-infection) in BAL and serum, in both experimental groups." (PMID 24691464, 2014). "The splenocytes of infected/WT mice exhibited a predominance of TNF-α (TNF-α>IL-10>IFN-γ) release throughout the course of infection." (PMID 25474113, 2014). "Yet, absence of MIF slightly increased survival time and reduced serum IFN-γ, TNF, and IL-6 concentrations while inducing IL-10 production in the chronic stage of infection." (PMID 25255103, 2014). "Multiparametric flow cytometer analysis of stimulated spleen cells shows that mice immunized with pcDNA-mGMCSF-LdPx1 kept high IFN-γ, TNF-α, and IL-2 response eight weeks post-infection." (PMID 25500571, 2014). "Th-1 cytokines such as IFN-γ, TNF-α, and IL-2 favor resistance to infection while IL-4, IL-10 and IL-13 mediate disease progression and parasite persistence." (PMID 25500571, 2014). "Inflammation is a natural response to damage and/or infection that are mediated by pro-inflammatory cytokines including interleukin 1 beta (IL-1β), interleukin 6 (IL-6), and tumor necrosis factor alpha (TNFα)." (PMID 25228881, 2014). "In line with this we observed increased expression of the proinflammatory cytokines IL-6 and TNFα peaking at day 3 or 5 post infection, respectively, and subsiding at day 7 after the infection." (PMID 24918427, 2014). "The IR/100 patient-years of all infections was 36.3 ranging from 12.4 (DMARDs + CS) to 62.7 (anti-TNFα + CS)." (PMID 24655394, 2014). "Macrophages have been reported to be the major source of interferon α/β, which plays a key role in viral clearance, and are important sources of IL-1β, IL-6 and TNF-α, which are responsible for the acute phase response to the infection." (PMID 25232724, 2014). "J774A.1 cells, pre- infection treated with LieIF/IFN-γ combined with anti-TNF-α monoclonal antibody produced significantly lower amounts of ROS compared to J774A.1 cells pre- infection treated with LieIF/IFN-γ only (p = 0.003)." (PMID 24830439, 2014). "The pro-inflammatory marker TNF-α was higher in the WAT of HFD-fed mice at this time point of infection." (PMID 25275627, 2014). "Since NK cells produce cytokines like TNF-α, this can explain the higher cytokine production following primo-infection at nine weeks of age." (PMID 25252649, 2014). "As expected, due to the expression of a large number of NF-κB inhibitors, infection of A549-NF-κB-LUC cells with VACV Copenhagen inhibited NF-κB reporter activity in response to TNF-α and IL-1β stimulation." (PMID 24371075, 2014). "We reasoned that if a window of opportunity existed to alter the infection productivity, treatment of cells with TNFα outside of this window should only have transient effects on the productivity of RGH infection." (PMID 24502247, 2014).
infection (continued). "As expected, p65 translocated into the nucleus in mock-infected cells that had been stimulated with TNF-α or IL-1β, and this was inhibited in the presence of vv811WT infection." (PMID 24371075, 2014). "This suggests that, besides the influence of the pregnancy, infection with C. burnetii also increases expression of TNF-α mRNA." (PMID 25279829, 2014). "The ELISA assay showed that TNF-α secretion was up-regulated after 4 and 8 hours of infection by influenza viruses, and it returned to basal levels after 24 hours of infection." (PMID 25105760, 2014). "To investigate the effect of mycobacterial infection on the tumorigenic properties of alveolar epithelial cells, we performed co-treatment of A549 cells with BCG and TNF-α, a primary cytokine produced during infection." (PMID 25208737, 2014). "In murine pulmonary responses to A. fumigatus, dectin-1 mediated TNF-α production and provided protection from infection." (PMID 24945802, 2014). "It has been observed that macrophages from patients with CL and ML that are infected with L. braziliensis produce large amounts of TNF-α when compared with macrophages from individuals with subclinical infection by L. braziliensis." (PMID 24485388, 2014). "WNV infection resulted in a 3- to 10-fold increase in the mRNA expression of cytokines such as IL-1β, TNF and IFNγ in the brains of WT mice at day 8 after infection compared to corresponding mock-infected mice." (PMID 24750819, 2014). "The cytokine studies with heat-killed EBs showed that TNF was induced by active infection of DCs by serovars D and L2." (PMID 25123797, 2014). "It has been reported that during the infection of Mycobacterium tuberculosis, TNF-a and nitric oxide are the most important pro-apoptotic mediators." (PMID 25000291, 2014). "Three days post infection, the increase of TNF levels in Ncf1 mutant lung was massive (3.6-fold compared to wild-type) and also observed at four weeks post-infection." (PMID 25188296, 2014). "During infection, TNF-α is a mediator between the immune system and the intestinal epithelial barrier by altering tight junction proteins and their cellular localization." (PMID 24673930, 2014). "LysM-Myd88−/− mice showed a strongly impaired neutrophil influx into the bronchoalveolar space 6 hours after infection with Klebsiella, together with markedly reduced local concentrations of neutrophil attracting mediators such as TNF-α, CXCL1 and CXCL2." (PMID 25254554, 2014). "On the other hand, intermediate TNF-α levels, as seen in individuals who are heterozygous for LTA4H, result in moderate inflammation, controlled infection and low risk of severe disease or death." (PMID 24997190, 2014). "In accordance with greater inflammatory cytokine secretion in the Siglec-E deficient macrophages following WT GBS stimulation, WT GBS also stimulated greater TNF-α secretion the Siglec-E KO microglia cells 24 h post infection." (PMID 24391502, 2014). "In this study, the expression profiles of the studied cytokines in terms of fold change (IFN-γ > IL-4 > IL-12p40 > TNF-α ≥ IL-10) were consistent with those demonstrated in previous studies of early infection when foetal death prevailed." (PMID 24479988, 2014). "Acute phase responses is induced by infection or trauma, and mediated by cytokines like IL-6 and TNF-α." (PMID 25153531, 2014). "In particular, the activation of TLR-9 signaling in pDCs induces a rapid production of IFN-α and tumor necrosis factor α (TNF-α), promoting, in turn, the migration of leucocytes from the bloodstream to the site of infection." (PMID 28548068, 2014). "In the mouse model, we detected strong increased levels of the pro-inflammatory cytokines TNFα and IL-6 in the brain during early infection, which coincided with a massive increase in C. glabrata cell number in this organ." (PMID 25356907, 2014). "TNF-α plays a crucial role in intracellular infection by activating macrophages and by promoting migration of other immune cells to the site of infection." (PMID 25329064, 2014).
infection (continued). "Cyp2a4/5 mRNA expression was increased by infection, and this effect was abolished by XPro1595 given from day −2 indicating a role for TNFα in the induction of Cyp2a4/5 during C. rodentium infection." (PMID 24707356, 2014). "The TNF-α blocking agent etanercept increased the efficacy of conventional antibiotics during the chronic phase of infection, when the bulk of the bacterial are thought to be replicating slowly." (PMID 24586159, 2014). "TNF-α promoted infection of HCVpp expressing a diverse panel of patient-derived envelope glycoproteins (data not shown)." (PMID 24259385, 2014). "The MIP-1α and TNF-α gene expressions in J774A.1 cells treated with LieIF/IFN-γ pre- or post-infection were determined by quantitative real-time PCR." (PMID 24830439, 2014). "MG, which is a central nervous system immune cell, plays a similar role in the brain macrophage cell function, and in the action against infection, MG is activated into reactive MG, which secretes inflammatory factors, such as TNF-α, IL-1 and TGF-β." (PMID 25372040, 2014). "In serum 24 hours after infection, TNF-α, MIP-2, and Il-1β levels were low but KC was readily detectable and higher in Nlrc4−/− mice compared to Casp1−/−Casp11−/− mice." (PMID 25232720, 2014). "In our study, after infection with S. japonicum for three weeks, cytokines (such as IL-4, IL-5, IL-6, IL-13, TNF-α and GM-CSF) in the sera of M. fortis were significantly increased, whereas cytokine levels of the BALB/c mice were much lower (data not shown)." (PMID 24886088, 2014). "Analysis of blood chemistries at 48 hours after infection of the CD11c Cre+Ifnarf/f and Ifnar−/− mice following anti-TNF-α treatment revealed improved AST, ALT, and glucose levels that were not different from WNV-infected Cre−Ifnarf/f control mice." (PMID 24743949, 2014). "On week 9 after infection, significant differences between treatments in the total frequencies of TNF-α (p = 0.0077) and IL-2-producing-CD4+ T cells of the spleens (p = 0.0035) were found." (PMID 24966857, 2014). "Although CCR2−/− mice have diminished levels of circulating Ly6Chi monocytes, they have increased numbers in the bone marrow at rest, and large numbers of activated TNF-α producing Ly6Chi monocytes accumulate in the bone marrow during infection." (PMID 24945711, 2014). "At the time of infection, a bacterial component such as lipopolysaccharide or a cytokine such as tumor necrosis factor-α (TNF-α) or interleukin-6 (IL-6) induces high expression of the calcitonin-I gene, which activates the continuous release of PCT." (PMID 25960877, 2014). "Here, in vitro infection showed that both isolates induced a strong production of NO and the cytokines TNF-α, IL-6, IL-1α, IL-1β, and IL-10." (PMID 24886263, 2014). "We analyzed the concentrations of the cytokines IL-12p70, IL-12p40, IL-10, IL-6 and TNF-α in supernatants of BMDC 48 hours after infection with L. major promastigotes, or stimulation with LmAg." (PMID 25255101, 2014). "Previously we have shown that TNF enhances infection of LCs by R5 HIV-1, and thereby increases transmission of R5 HIV-1." (PMID 24990163, 2014). "IL-6 is a cytokine that shows early response to infection, preceding the increase in C-reactive protein and followed by TNF-α release." (PMID 25614712, 2014). "Previous studies demonstrate that anti-inflammatory agents such as monoclonal antibodies to TNF increase septic shock lethality due to suppression of the host's ability to fight infection." (PMID 25054155, 2014). "An important finding was the elevated levels of TNF-α mRNA during the acute phase of infection with Querétaro strain." (PMID 24991553, 2014). "Statistically significant increases in total percentages of CD4+IFNγ+, CD4+IL-2+, and CD4+TNFα+ T cells were detected post-infection relative to D0 (P<0.05, 0.01, and 0.05, respectively) following primary infection." (PMID 25397604, 2014).
infection (continued). "Tumor necrosis factor α (TNFα) is a multifunctional cytokine that mediates key roles in acute and chronic inflammation, antitumor responses, and infection." (PMID 24802997, 2014). "In a separate study, IL-6, TNFα, IL-8, and IL-15 were significantly higher in the group with severe pH1N1 infection when a panel of nine serum cytokines was analyzed." (PMID 25003343, 2014). "YopE69–77-immunized mice that completely lack the ability to produce either TNFα or IFNγ succumb to infection, suggesting that each of these cytokines are absolutely required for CD8 T cell-mediated anti-Yersinia immunity." (PMID 24854422, 2014). "While TLR3 ablation protected mice from WNV lethal infection by decreased systemic TNF-α and IL-6 production and BBB permeability, there is a report demonstrating that TLR3 molecules are essential in protecting from WNV infection." (PMID 25188232, 2014). "In contrast, the infection with P. berghei ANKA induces high levels of IFN-γ and TNF-α which are associated with cerebral malaria." (PMID 25276830, 2014). "We found that peripheral monocytes recognized the presence of live GC-FA19 infection and robustly responded by releasing cytokines IL-6 and TNFα as well as the antibacterial lipocalin NGAL, and by upregulating hepcidin gene expression." (PMID 24489950, 2014). "In conclusion, we demonstrate a new pathway for HCV to exploit macrophage-expressed TNF-α to promote infection." (PMID 24259385, 2014). "TNF-α and nitric oxide produced by TipDCs contribute to tissue injury and liver necrosis during infection with Trypanosoma brucei." (PMID 24945711, 2014). "In order to characterize the effect of immunization with the inactivated LPS deficient vaccine on cytokine levels, sera were collected from vaccinated and control mice 12 h post-infection and the levels of IL-1β, IL-6 and TNF-α were determined." (PMID 25485716, 2014). "Gp120 is shed from the mature virion in vitro, has been detected in the plasma of patients early during the infection and correlated with higher levels of TNF-α, IL-6, IL-10, INF-α, and IFN-γ." (PMID 25309527, 2014). "Interleukin-1β has as main source macrophages stimulated by TNF-α or bacterial LPS and is responsible for promoting the recruitment of leukocytes to the infection site." (PMID 24757289, 2014). "Our data shows that following primary infection in all subjects, peripheral C. jejuni-specific CD4+ T cells produce pro-inflammatory cytokines, including IFNγ and TNFα, peaking 7-14 days post-infection." (PMID 25397604, 2014). "WNV-induced expression of pro-inflammatory cytokines such as IL-1β and TNF regulate leukocyte trafficking into the brain, and neuronal death after infection." (PMID 24750819, 2014). "KCs and peripheral-derived cells responded to LPS and expressed comparable levels of TNF-α and increased HCVpp infection." (PMID 24259385, 2014). "There was a trend towards a correlation between CD3+ T cells in BAL and levels of TNF-α in BAL at infection." (PMID 24099891, 2014). "Infection of type II P.gingivalis also exhibited prolonged cytokine response such as IL-1b, IL-8 and TNFα." (PMID 24466164, 2014). "At 12 hours post-infection, cells were stimulated with TNFα, fixed and stained with anti-IκBα or anti-I3L, an early poxvirus protein that is indicative of infection, and analyzed by flow cytometry." (PMID 25122471, 2014). "The untreated-Ab-infected group displayed significantly lower levels of TNF-α (P<0.05) than untreated controls 24 h post-infection." (PMID 24752133, 2014). "Along with the invasion ability, the expression of TNF-α induced by infection was suppressed simultaneously by the treatment—also in a dose-dependent manner." (PMID 25133542, 2014). "Using the mouse macrophage line RAW264.7 to investigate the effect of TcpF on host immune cells, we found that infection with the tcpF deletion mutant of E. faecalis strainSymbioflor 1 led to significantly higher TNF-α response as compared to wild-type." (PMID 25147569, 2014).
infection (continued). "In wild-type mice, production of IL-12/23p40 and TNF was up-regulated in lung homogenates 21, 42 and 63 days after aerosol infection with Mtb." (PMID 24979482, 2014). "Infected cells were treated daily with TNF until day 4 post-infection, or with a single dose of FSL-1 just after infection, and the mycobacterial growth was then measured at different time-points for up to 7 days, by counting CFUs." (PMID 25400920, 2014). "We detected changes in the mRNA levels for a few genes in L. major-infected RAW cells, and of relevance, there was PKR-dependent increased expression of TNF-α on infection with Δisp2/isp3." (PMID 24732131, 2014). "Our results showed that L. donovani-infected J774A.1 cells pre-infection treated with LieIF/IFN-γ had a 9-fold up-regulation in TNF-α mRNA expression at the late time point (72 h) of infection." (PMID 24830439, 2014). "Two days post-infection, neurons were treated for 20 h with either Aβd/t (∼250 pM) or TNFα (50 ng/ml), fixed, immunostained for cofilin (Alexa 594 secondary antibody), and infected neurons (GFP positive) scored for rod formation." (PMID 24760020, 2014). "Orchidectomy at day 60 post-infection produced a significant decrease of bacilli burdens in coexistence with higher expression of TNFα, IL-12 and IFNγ." (PMID 24722144, 2014). "By 48 hours after infection, TNF-α levels in Casp1−/−Casp11−/− mice were significantly greater than wild type." (PMID 25232720, 2014). "When we tested for cytokine induction in mouse macrophages by the different strains we found identically increased levels of TNFα release after infection with both, the evolved and the CHSEvo strain." (PMID 25356907, 2014). "Although the source remains to be determined, it is likely that macrophage-derived TNF acts in autocrine and paracrine ways to facilitate chemotactic relocation of macrophages to the site of infection." (PMID 25325020, 2014). "Infection of bovine epithelial cells and monocytes with rBRSVΔSH, in vitro, resulted in an increase in apoptosis, and higher levels of TNF-α and IL-1β compared with cells infected with parental, wild-type (WT) rBRSV." (PMID 24700100, 2014). "In the present study, we showed that infection by fully virulent B. anthracis spores induced not only transcriptional upregulation of tlr9 but also production of TNF-α in murine macrophage RAW264.7 cells." (PMID 25472474, 2014). "Specifically, activated MC release factors such as tumor necrosis factor α (TNFα), histamine, proteases, and chemokines that are known to increase vascular permeability at sites of ongoing infection." (PMID 24763809, 2014). "VCG activation of BMDC enhanced the secretion of proinflammatory cytokines, particularly IL-12 and TNF-α and chlamydial antigen presentation to infection-sensitized CD4+ T cells leading to enhanced proliferation and secretion of Th1-type cytokines." (PMID 25551828, 2014). "Based on these observations including us, it is possible that the concentration of BAG in the blood of infected animal in the late phase of infection would be high enough to induce TNF-α." (PMID 25472474, 2014). "Infection of macrophages with the lsfA mutant strains resulted in higher levels of the cytokine TNF-α production due to the activation of the NF-kB and MAPK pathways, that are partially inhibited by the wild-type P. aeruginosa strain." (PMID 25329795, 2014). "The production of TNF-α, IL-6 and IL-8 by cervical lymph node MC was significantly higher for the control animals than for the infection or the re-infection group." (PMID 25252649, 2014). "Treatment of mice with either AMP or AZM alone or in combination after infection was able to significantly down regulate the serum TNF- α, IFN- γ and IL-6 levels at 2, 3, 4, 5 and 6 hours post antibiotic treatment." (PMID 24565171, 2014).